SHBG (sex hormone binding globulin)
Diseases named in the same sentence as SHBG in open-access papers (continued):
Sharing a sentence is not in itself a finding about the gene and the disease.
hyperandrogenism (continued). "Because the bioactivity of androgens is determined by the free-testosterone, SHBG levels are important in the evaluation of hyperandrogenism." (PMID 33139661, 2020). "SHBG produced by the liver, a transporter of sex hormones with a high affinity for T but a low affinity for E2, can be used to evaluate the severity of hyperandrogenism and the therapeutic efficacy." (PMID 32670195, 2020). "Serum DHEAS, testosterone, SHBG and free androgen index (FAI) are used as diagnostic markers of hyperandrogenism." (PMID 31814932, 2019). "This study found that there were three biochemical parameters that significantly differed between the two groups and correlated with hyperandrogenism phenotype, which were elevated testosterone and triglyceride levels, as well as decreased SHBG level." (PMID 30881692, 2019). "The hyperandrogenism group had significantly higher level of triglyceride and testosterone, but lower SHBG level." (PMID 30881692, 2019). "In our study, serum SHBG levels below 30 nmol/L, as typically found in androgen excess, conferred an almost 5-fold increase in the hazard of NAFLD." (PMID 29590099, 2018). "SHBG is a plasma protein for androgen and estrogens and so decreased SHBG levels can lead to hyperandrogenism in PCOS." (PMID 30299265, 2018). "It has been reported that T levels cannot reflect hyperandrogenism precisely because 85% of total T is combined with SHBG in circulation with little biological activity." (PMID 29074860, 2017). "The presence of hyperandrogenism reduces the hepatic synthesis of SHBG and leads to a relative excess of free circulating androgens." (PMID 27635134, 2016). "Therefore, SHBG is an effective auxiliary marker for the determination of androgen levels and can be used to estimate the severity of hyperandrogenism." (PMID 39996383, 2025). "Previous studies have shown that metformin reduces hyperandrogenism by suppressing ovarian theca cell androgen production and increasing sex hormone-binding globulin (SHBG) levels, which is consistent with our finding of a stronger effect of metformin on androstenedione reduction." (PMID 41010765, 2025). "PCOS itself does not lead to an increase in OS levels, and the increase in OS levels in PCOS is related to other potential factors, such as hyperandrogenism, low-density lipoprotein, high-density lipoprotein, sex hormone-binding globulin, body mass index, triacylglycerol, and age at menarche." (PMID 37337194, 2023). "Also, hyperandrogenism and low sex hormone-binding globulin are involved in the development of CVDs." (PMID 37025693, 2023). "Importantly, COCP improves hyperandrogenism via different mechanisms, primarily by stimulation of sex hormone binding globulin (SHBG) production, the major binding protein for testosterone, thereby decreasing free circulating androgens." (PMID 36939017, 2023). "Additionally, the FAI score and the percentage of patients with hyperandrogenism decreased, while SHBG levels increased significantly." (PMID 37242145, 2023). "The hallmark of hormonal imbalance is hyperandrogenism manifesting biochemically as an elevation of testosterone (T) and increased free androgen index (FAI), with the latter reflecting an increase in the T:SHBG ratio." (PMID 35265039, 2022). "In contrast, the links between hyperandrogenism and upper-body fat distribution and dyslipidaemia might be indirect and driven by lower SHBG levels." (PMID 35049520, 2022). "Liver synthesis of SHBG is reduced not only by hyperinsulinemia, but also by hyperandrogenism." (PMID 36009471, 2022). "This oxidative stress may promote hyperandrogenism by reducing levels of the sex hormone-binding globulin." (PMID 36406137, 2022). "Considering this hypothesis, insulin could elevate androgen biosynthesis and reduce sex hormone-binding globulin (SHBG) which resulted in hyperandrogenism." (PMID 34362981, 2021). "Low serum-SHBG concentration is often used as an indicator of hyperandrogenism in women with PCOS." (PMID 34805198, 2021).
hyperandrogenism (continued). "We may notice the elevation of testosterone (T) levels in both PCOS groups (median >0.5 ng/mL) as well as typical for hyperandrogenism drop in the level of sex-hormone globulin (SHBG) in PCOS populations." (PMID 34202365, 2021). "Moreover, insulin, by lowering liver sex hormone–binding globulin (SHBG) production, increases androgen bioavailability at target organs, further contributing to clinical signs of hyperandrogenism." (PMID 32849300, 2020). "SHBG is considered to be a plasma protein for androgen and estrogens; therefore, any decrement in SHBG levels could result in hyperandrogenism in PCOS sufferers." (PMID 31611740, 2019). "However, the data indicate that the participants in the meta-analysis had low enough SHBG concentrations (<30 nmol/L), even post-intervention, to indicate hyperandrogenism." (PMID 31890686, 2019). "The lifestyle intervention was not improved by the addition of herbal medicine for biochemical hyperandrogenism including testosterone, SHBG or FAI, gonadotropin hormones FSH or the FSH LH ratio, metabolic measurements of fasting glucose or insulin sensitivity or anthropometric hip‐to‐waist ratio." (PMID 28685911, 2017). "Additionally, insulin has been shown to lower sex hormone binding globulin, which can lead to increased free androgen levels and clinical hyperandrogenism." (PMID 28620546, 2017). "However, women with PCOS generally have hyperandrogenism and lower SHBG and differences at the end of the intervention are again likely related to baseline differences." (PMID 28885578, 2017). "Increases in serum SHBG in women under these conditions undoubtedly influence the plasma distribution of both androgens and estrogens, and this property has been exploited therapeutically to reduce androgen exposures in women with symptoms of hyperandrogenism." (PMID 27113851, 2016). "Insulin may lead to hyperandrogenism by reducing SHBG production in the liver and also by increasing the amount of circulating free testosterone, a biologically active androgen." (PMID 26761944, 2016). "As compared to healthy controls, females with PCOS (particularly in the PCOS-NIH subgroup) showed significantly higher BMI and WC, dyslipidemia and a characteristic sex hormone profile with clinical or biochemical hyperandrogenism as well as decreased SHBG (sex hormone binding globulin) levels." (PMID 27505055, 2016). "Serum DHEAS, testosterone, SHBG and FAI are used as diagnostic markers of hyperandrogenism." (PMID 26061015, 2015). "Moreover, oral contraceptives provide direct negative feedback on LH secretion, leading to reduced ovarian production of androgens and consequently lowering hyperandrogenism and raising sex hormone-binding globulin levels in the liver, which decreases the amount of free circulating androgens." (PMID 39459443, 2024). "Finally, changes in the genus Senegalimassilia were correlated with markers of hyperandrogenism such as testosterone levels (r = −0.284, p = 0.026), SHBG levels (r = 0.429, p = 0.001), FAI (r = −0.440, p = 0.001), liver fat (r = −0.352, p = 0.007), and central (visceral) fat (r = −0.309, p = 0.018)." (PMID 38136074, 2023). "The major clinical or biochemical features of hyperandrogenism are acne, hirsutism, alopecia, and seborrheic dermatitis; elevated testosterone, androstenedione, and dehydroepiandrosterone sulfate levels; and decreased sex hormone binding globulin (SHBG) levels." (PMID 32903374, 2020). "The positions of SHBG and testosterone, relative to PC1 and PC2, demonstrate the contribution of each to hyperandrogenism." (PMID 41180187, 2025). "Combined oral contraceptive pills help to treat biochemical hyperandrogenism by suppressing ovarian androgen production and increasing the production of SHBG (sex hormone-binding globulin), which in turn decreases the free androgen levels." (PMID 38398368, 2024).
hyperandrogenism (continued). "Concerning fertility, intermittent fasting has been shown to reduce androgen levels and raise sex hormone-binding globulin (SHBG) levels in obese women, as well as reduce hyperandrogenism, and improve menstruation rates and fertility in females with PCOS." (PMID 39649353, 2024). "The high concentration of insulin can regulate the production of free testosterone and lead to hyperandrogenism through the increase of free insulin‐like growth factor I (IGF‐I) and sex hormone‐binding globulin (SHBG)." (PMID 37823091, 2023). "Hyperandrogenism is one of the main symptoms in patients with PCOS, and serum TT, DHEAS, SHBG levels, and free androgen index (FAI) are used for diagnosis." (PMID 38222239, 2023). "The pathophysiologic processes of both IR and hyperandrogenism seem to connect PCOS with NAFLD, and SHBG seems to be a key factor in both disorders." (PMID 37685811, 2023). "Concomitantly, the increased levels of insulin reduce the binding of liver sex hormone binding globulin SHBG to testosterone, leading to hyperandrogenism." (PMID 34497589, 2021). "In women with PCOS and hyperandrogenism, TZD treatment increases sex hormone binding globulin (SHBG) levels in plasma, leading to a decrease in free-circulating testosterone levels." (PMID 20144211, 2010). "Studies that reported sex hormones, SHBG or hyperandrogenism with sleep problems included total, free, and bioavailable testosterone, DHEAS, SHBG, androstenedione, oestradiol, hirsutism and FAI." (PMID 39996383, 2025). "Additionally, low SHBG correlates strongly with hyperandrogenic symptoms, making it an essential clinical marker for diagnosing and managing PCOS-related hyperandrogenism." (PMID 40385768, 2025). "In line with our previous studies, PCOS animals showed excess body weight gain/ovarian mass, abnormal metabolic indices (fasting insulin, blood glucose and HOMA-IR), androgen excess, multiple ovarian cysts, elevated AMH and leptin and decreased SHBG, adiponectin and 17-β estradiol." (PMID 38561673, 2024). "Oxidative stress hinders the production and release of SHBG by reducing the activity of HNF-4α, which could potentially play a significant role in the development of hyperandrogenism in PCOS." (PMID 38589892, 2024). "Fourth, the use of other biochemical parameters of hyperandrogenism such as FAI, SHBG, and anti-müllerian hormone (AMH) might have been more accurate in the assessment of the association between myonectin and hyperandrogenism." (PMID 35700181, 2022). "In conclusion, the authors suggested that in post-adolescent women, acne severity appears to depend on peripheral hyperandrogenism, with a negative correlation between acne severity and serum SHBG levels." (PMID 36552842, 2022). "A recent Mendelian randomization study showed that genetically predicted SHBG, total testosterone and free testosterone levels were associated with PCOS risk, which is not surprising given the adoption of hyperandrogenism as a diagnostic criterion of PCOS." (PMID 34277990, 2021). "Concerning the biochemical evaluation of hyperandrogenism, serum SHBG measurements were not available and were limited to total testosterone, which is less sensitive than the free androgen index to detect subtle hyperandrogenemia." (PMID 32555989, 2020). "Typically, the baseline values of women with PCOS included in this current review were below recommended cut-offs for diagnosing hyperandrogenism; testosterone > 2.5 nmol/L and SHBG < 30 nmol/L, which indicates that they were not markedly hyperandrogenic." (PMID 30755271, 2019). "Within bivariate analysis, significant differences between hyperandrogenism and non-hyperandrogenism group were observed in some characteristics, such as triglyceride level (p = 0.01), SHBG level (p = 0.01), and testosterone level (p = 0.04)." (PMID 30881692, 2019).
hyperandrogenism (continued). "Pathophysiological functions of genes are primarily responsible for the synthesis of proteins that have role in PCOS before hyperandrogenism including GnRHR, FSHβ, FSHR, LHCGR, CYP19A1, HSD17B, AR and SHBG, and their effects in PCOS of human have been confirmed." (PMID 30944702, 2019). "The normal SHBG levels in women with T1D and PCOS may explain their milder hyperandrogenism when compared with women in the general population: hirsutism was not usually present in these women, and their FT was reduced compared to typical women with PCOS despite similar TT levels." (PMID 40747135, 2025). "However, the pathophysiological reason for sleep problems in PCOS is not clear with some, but not all prior research reporting links between hyperandrogenism or SHBG and OSA or other sleep disturbances in PCOS." (PMID 39996383, 2025). "This indicates that lower levels of SHBG, rather than hyperandrogenism, may play a more important mechanistic role for OSA in PCOS." (PMID 39996383, 2025). "SHBG, rather than hyperandrogenism, may play a more important mechanistic role for OSA in PCOS, while other sleep disturbances exhibit a less severe SHBG profile." (PMID 39996383, 2025). "However, when analyzing separately normal and overweight patients with PCOS, we found differences not only in dyslipidemia and atherogenic lipid profile but also in more pronounced hyperandrogenism according to the increased level of FAI and decreased SHBG in overweight PCOS group." (PMID 32545404, 2020). "One the other hand, the role of SHBG in the evaluation of adult PCOS may be less important because adult women with or without PCOS often take the combined oral contraceptives (COCs) either for pregnancy prevention or for menstrual regularity and hyperandrogenism." (PMID 33139661, 2020). "Hyperandrogenism is often a common feature between the two conditions and in both, the manifestation of this hyperandrogenism may not correlate with the circulating androgen levels because total circulating testosterone is mostly bound to albumin and sex-hormone binding globulin." (PMID 24719635, 2013). "This combined COC containing DSG blocks the estrogen-mediated increase in SHBG more than other antiandrogenic progestins and would not be the first choice for women with PCOS, mainly for those with biochemical hyperandrogenism." (PMID 29216881, 2017). "Decrease of SHBG and increase of FAI after berberine treatment showed berberine had no obvious efficacy on hyperandrogenism." (PMID 26645811, 2015). "Laboratory assessment in suspected PCOS involves measuring total and free testosterone, sex hormone-binding globulin (SHBG), dehydroepiandrosterone sulfate (DHEAS), and 17-hydroxyprogesterone to evaluate for hyperandrogenism and rule out late-onset congenital adrenal hyperplasia." (PMID 41268159, 2025).
breast cancer (153 papers, 1985 to 2026). A primary or metastatic malignant neoplasm involving the breast. "This decline in SHBG contributes to higher levels of free estrogen in the bloodstream, which is associated with an increased risk of breast cancer among postmenopausal women." (PMID 41463284, 2025). "The testosterone–SHBG ratio also exhibited a significant association with breast cancer risk in the placebo group (trend 1.21, 95% CI 1.05 to 1.41, p= 0.011) but not in the anastrozole group." (PMID 40599862, 2025). "Higher concentrations of sex hormone-binding globulin (SHBG) have been associated with a reduced risk of breast cancer." (PMID 39858629, 2025). "The higher fat levels were associated with higher levels of serum estrone and estradiol and lower levels of sex hormone-binding globulin, which is linked to an increased risk of breast cancer." (PMID 39609539, 2025). "Anastrozole demonstrated a clear benefit in reducing breast cancer risk across all quartiles of estradiol–SHBG ratio." (PMID 40599862, 2025). "The Endogenous Hormones and Breast Cancer Collaborative Group reported a significant increase in BC risk with higher levels of total, free, and non-sex-hormone-binding globulin (SHBG)-bound estradiol in postmenopausal women." (PMID 40731797, 2025). "Many factors can affect the plasma SHBG levels, with fluctuations in circulating levels affecting the development of various diseases, such as increasing the risk of developing breast cancer." (PMID 38465341, 2024). "By means of bioinformatics analysis, we found that SHBG expression in breast tissue can effectively distinguish breast cancer from normal tissue and investigated the association between SHBG expression levels and several tumor-related pathways." (PMID 38465341, 2024). "These metabolic changes stimulate ovarian androgen synthesis and inhibit SHBG production, resulting in elevated testosterone levels and enhanced estradiol bioavailability, thereby increasing the risk of breast cancer." (PMID 39791640, 2024). "Elevated levels of testosterone and C-reactive protein (CRP) have been associated with an increased risk of breast cancer, whereas higher levels of sex hormone-binding globulin (SHBG) correlate with a reduced risk." (PMID 39791640, 2024). "Decreasing levels of sex hormone binding globulin (SHBG) reveals a positive effect on estrogen bioavailability, causing an increased risk of breast cancer." (PMID 38397072, 2024). "SHBG is one of the factors that regulate estrogen balance, and therefore, it must be considered when assessing the risk of breast cancer in elderly women." (PMID 38465341, 2024). "A small number of studies based on tumor receptor status have concluded that low SHBG levels increase the risk of ER-positive breast cancer more significantly than overall breast cancer." (PMID 38465341, 2024). "The sensitivity of breast cancer cells to estrogen is closely associated with the interaction between SHBG and cell membranes." (PMID 38465341, 2024). "A recent systematic review and meta-analysis found moderate- to high-quality evidence that higher levels of estrogens and androgens, and lower levels of sex-hormone binding globulin (SHBG), were associated with increased risks of postmenopausal breast cancer." (PMID 38363402, 2024). "In our “top list” with the 36 most important findings, a study of breast density had the highest effect size for increasing the risk of breast cancer, and a high sex-hormone-binding globulin level was the most protective factor." (PMID 38672665, 2024). "In our work, the associations of GWAS (genome-wide associative studies) impact for sex-hormone-binding globulin (SHBG)-level SNPs with the risk of breast cancer (BC) in the cohort of Caucasian women of Russia were assessed." (PMID 38396861, 2024). "Beyond SHBG, Chen and colleagues found associations between fasting insulin levels and increased risk for breast cancer." (PMID 37377609, 2023).